DAZAP1 (DAZ associated protein 1)
Description:
RNA-binding protein, which may be required during spermatogenesis.
Synonyms: MGC19907
Tractability: Small molecule: it has a binding pocket of medium quality. PROTAC: ubiquitination databases record sites on it; its protein half-life has been measured.
Gene: Protein-coding gene on chromosome 19 (1,407,536 to 1,435,687, forward strand). Ensembl gene ENSG00000071626.
Subcellular location: Cytoplasm; Nucleus
Subcellular location (Human Protein Atlas): Nucleoplasm; Cytosol; Midbody
Gene Ontology:
Molecular function: poly(G) binding; poly(U) RNA binding; protein binding; RNA binding; mRNA 3'-UTR binding; nucleic acid binding; RNA stem-loop binding
Biological process: positive regulation of mRNA splicing, via spliceosome; spermatogenesis
Cellular component: cytosol; nucleoplasm; protein-containing complex; ribonucleoprotein complex; nucleus; perinuclear region of cytoplasm; cytoplasm
Genetic constraint (gnomAD): Loss-of-function variants: 6 observed, 50.14 expected, observed/expected ratio (o/e) 0.12, 90% interval 0.065 to 0.24. The upper end of that interval is the gene's LOEUF score, 0.24, which puts it in group 1 of 6, group 1 being the genes least tolerant of losing a copy. Missense variants: 316 observed, 501.26 expected, observed/expected ratio (o/e) 0.63, 90% interval 0.57 to 0.69. Synonymous variants: 205 observed, 196.03 expected, observed/expected ratio (o/e) 1.05, 90% interval 0.93 to 1.17.
Homologues: Orthologues: dog DAZAP1 (99% identical), pig DAZAP1 (99% identical), mouse Dazap1 (98% identical), chimpanzee DAZAP1 (95% identical), rat Dazap1 (94% identical), guinea pig DAZAP1 (87% identical), tropical clawed frog dazap1 (84% identical), macaque DAZAP1 (84% identical), zebrafish dazap1 (69% identical), Caenorhabditis elegans hrpa-1 (30% identical), Drosophila melanogaster Rbp4 (27% identical). Paralogues in human: MSI2 (31% identical), MSI1 (30% identical), HNRNPA1 (25% identical), HNRNPA3 (25% identical), HNRNPA1L3 (24% identical), HNRNPDL (24% identical), HNRNPA1L2 (24% identical), HNRNPA2B1 (24% identical), HNRNPA0 (24% identical), HNRNPAB (24% identical), HNRNPD (24% identical), RBMX (22% identical), and 24 more.
Diseases named in the same sentence as DAZAP1 in open-access papers:
DAZAP1 is named in the same sentence as 25 diseases in open-access papers, as found by Europe PMC text mining. Sharing a sentence is not in itself a finding about the gene and the disease. The quoted sentences say what the papers report.
Azoospermia (3 papers, 2020 to 2023). Absence of any measurable level of sperm,whereby spermatozoa cannot be observed even after centrifugation of the semen pellet. "Metabolic associations with genes known to associate with bladder cancer (BLCAP), ovarian cancer (OCIAD1), and infertility caused by azoospermia (DAZAP1) could highlight the importance of integrating both methylation and metabolomics for assessing T2D complications." (PMID 37679740, 2023). "The highly conserved RNA binding protein DAZAP1 was originally identified as a binding partner of DAZ (deleted in azoospermia) 32,33 and is involved in mammalian development and spermatogenesis." (PMID 32308763, 2020). "DAZAP1 was initially identified as an important binding partner of DAZ (deleted in azoospermia) and DAZL (deleted in azoospermia like), required for not only spermatogenesis but also the normal growth and development of mammals." (PMID 36242590, 2022).
esophageal squamous cell carcinoma (3 papers, 2020 to 2025). Esophageal squamous cell carcinoma (ESCC) is a type of esophageal carcinoma (EC) that can affect any part of the esophagus, but is usually located in the upper or middle third. "For instance, in esophageal squamous cell carcinoma, DAZAP1 knockdown led to marked changes in alternative splicing events." (PMID 40401521, 2025).
Infertility (3 papers, 2016 to 2023). "Furthermore, we found that the infertile mouse model most similar to human MArrest was the Dazap1 mutant mouse." (PMID 29150651, 2017). "Additionally, the Arpc1b gene was up-regulated in Bcl6b, Etv5, Pouf31 and Dazap1 KD, and Alcam was up-regulated in Bcl6b, Etv5, Pouf31 and Ing2 KD infertile mice." (PMID 29150651, 2017). "We compared nine types of infertility in male humans and mice, including MArrest, oligospermia and teratospermia in humans and Ing2 Knockout (KO), Bcl6 KD, Etv5 KD, Pou3f1 KD, Ikbkap KO and Dazap1 mutant in mice." (PMID 29150651, 2017). "Dazap1 is one of the isoforms of DAZ, and we observed the highest number of common genes between Dazap1 mouse mutants and MArrest cases, with 21 common down-regulated genes, in comparison to other infertile mice." (PMID 29150651, 2017).
multiple myeloma (2 papers, 2022 to 2025). "In multiple myeloma cells, DAZAP1 promoted cell proliferation by enhancing the alternative splicing of KITLG mRNA, activating the ERK signaling pathway." (PMID 40401521, 2025).
osteoarthritis (2 papers, 2023 to 2024). A noninflammatory degenerative joint disease occurring chiefly in older persons, characterized by degeneration of the articular cartilage, hypertrophy of bone at the margins and changes in the synovial membrane. "By targeting the DAZAP1 and MAPK pathways, upregulated miR-320a improved IL-1β-induced osteoarthritis by enhancing chondrocyte proliferation, reducing apoptosis, and decreasing inflammatory response." (PMID 38816719, 2024).
acute lymphoblastic leukaemia (1 paper, 2013). "A role of DAZAP1 in transcription is also supported by the exclusion of DAZAP1 from the transcriptionally inactive XY bodies in pachytene spermatocytes and the fusion of DAZAP1 to the MEF2D oncogene in a pre-B acute lymphoblastic leukaemia, and warrants further investigation." (PMID 23965306, 2013).
Diamond-Blackfan anemia (1 paper, 2023). A congenital aregenerative and often macrocytic anemia with erythroblastopenia. "DAZAP1 and MBD3 do not currently show any evidence for their involvement in CHD; however, a missense mutation in RPS15 has been described as a possible causal candidate in a patient with complex CHD as part of Diamond Blackfan anemia." (PMID 37887000, 2023).
gastric cancer (1 paper, 2025). A primary or metastatic malignant neoplasm involving the stomach. "DAZAP1 upregulation in gastric cancer promotes cell stemness through ULK1-mediated mitophagy and oxidative phosphorylation, revealing a key molecular mechanism in GC progression." (PMID 40401521, 2025).
male infertility (1 paper, 2022). The inability of the male to effect fertilization of an ovum after a specified period of unprotected intercourse. "Among the other validated hits were proteins involved in the ubiquitin proteasome system (STAMBP and MYLIP), transcription (MTA1, PKNOX2), translation (EIF4E3), male infertility (RABL2A, DAZAP1), and virus-induced oncogenesis (MTA1)." (PMID 35452674, 2022).
oligospermia (1 paper, 2017). Decreased number of spermatozoa in the semen. "Three down-regulated genes (PLCZ1, TSSK2 and ANKRD7) were common between MArrest, oligospermia and the Dazap1 mouse mutant." (PMID 29150651, 2017). "The highest number of common down-regulated genes was found between MArrest and oligospermia, with 32 genes, MArrest and the Dazap1 mutant, with 21 genes, MArrest and teratospermia, with 13 genes, and MArrest and Ikbkap KO, with 8 common genes." (PMID 29150651, 2017).
oral squamous cell carcinoma (1 paper, 2025). "DAZ associated protein 1 (DAZAP1) is significantly upregulated in oral squamous cell carcinoma (OSCC), and clinical samples have shown that high expression of DAZAP1 and cytochrome-c oxidase 16 (COX16) is associated with poor patient prognosis." (PMID 40642070, 2025).
prostate carcinoma (1 paper, 2021). A carcinoma that arises from epithelial cells of the prostate gland. "The lasso results also showed that five genes (AR, PDHA1, RAN, DPP4 and DAZAP1) were the powerful composed factors of prostate cancer risk prediction model." (PMID 33407865, 2021).
stomach adenocarcinoma (1 paper, 2025). "To further explore the role of DAZAP1 in GCSCs, we calculated the stemness index of The Cancer Genome Atlas stomach adenocarcinoma (TCGA-STAD) samples using the one-class logistic regression (OCLR) algorithm." (PMID 40401521, 2025).
synovial sarcoma (1 paper, 2016). "In total, a group of 42 cases are discovered with MEF2D rearranged to BCL9, CSF1R, DAZAP1 (DAZ (deleted in azoospermia)-associated protein 1), HNRNPUL1 (heterogeneous nuclear ribonucleoprotein U-like 1), SS18 (synovial sarcoma translocation, chromosome 18) or FOXJ2 (Forkhead Box J2)." (PMID 27824051, 2016).
cancer (6 papers, 2020 to 2025). A tumor composed of atypical neoplastic, often pleomorphic cells that invade other tissues. "In the first enriched pathway, surveillance pathway, five genes (HBS1L, DAZAP1, RBM8A, CSTF3, and CSTF2T) overlap, all of which have been previously implicated in cancer progression." (PMID 38305998, 2024). "Our findings indicate that DAZAP1 reduces ULK1 decay, thereby activating mitophagy and enhancing OXPHOS to fulfill the metabolic demands of cancer stem cells." (PMID 40401521, 2025).
tumor (4 papers, 2020 to 2025). "Studies on pathological splicing mutations support the importance for DAZAP1 in RNA splicing of several key tumor suppressors, such as NF1, BRCA1 and ATM38." (PMID 32308763, 2020). "Compared with the control group, the results showed that DAZAP1 knockdown substantially inhibited the tumor growth rate and weight." (PMID 40401521, 2025). "In summary, these data indicate that DAZAP1 not only markedly promotes the proliferation and migration of GC cells but also drives tumor progression and invasion by enhancing stemness characteristics." (PMID 40401521, 2025). "Cells were classified into high and low stemness groups based on the median CytoTRACE score, and the results demonstrated that DAZAP1 mRNA was higher in high-stemness tumor cells (P < 2.2 × 10–16)." (PMID 40401521, 2025). "DAZAP1 promoted tumor progression in GCSCs, as shown by sphere formation assays and stemness marker analysis." (PMID 40401521, 2025). "In vivo experiments using NCI-N87 cells for tumor formation assays were conducted to assess the impact of DAZAP1 on tumor growth." (PMID 40401521, 2025). "Functional enrichment analysis suggested that DAZAP1 enhanced tumor stemness by promoting oxidative phosphorylation (OXPHOS), which was validated through Seahorse assays and measurements of mitochondrial potential." (PMID 40401521, 2025). "In tumor epithelial cells, the CytoTRACE score was substantially and positively correlated with DAZAP1 expression (R = 0.38, P < 2.2 × 10–16)." (PMID 40401521, 2025). "DAZAP1 not only promotes the proliferation, migration, and invasiveness of GC cells but also exacerbates tumor progression by enhancing cellular stemness characteristics." (PMID 40401521, 2025). "In conclusion, we establish DAZAP1 as a tumor-promoting gene with therapeutic potential and provide mechanistic insights into targeting DAZAP1 as a new strategy for the diagnosis and treatment of MM." (PMID 36242590, 2022). "As a result, a mouse model with tumor-specific deletion of miR-10b in tumors arising spontaneously in mice would be a good tool to stablish the in vivo role of the miR10b/DAZAP1/TSC2 axis in ESCC in the future." (PMID 32308763, 2020). "Additionally, DAZAP1 mRNA levels were elevated in spheroid cells compared with corresponding adherent tumor cells." (PMID 40401521, 2025). "In summary, we demonstrate that DAZAP1 acts as a tumor-promoting gene with therapeutic potential." (PMID 36242590, 2022). "DAZAP1 promoted MM cell proliferation in vitro and accelerated MM xenograft tumor growth in vivo." (PMID 36242590, 2022). "The tumor suppressor function of DAZAP1 was further determined in ESCC cell lines." (PMID 32308763, 2020). "Our findings suggest that DAZAP1 acts as a crucial tumor suppressor in ESCC pathogenesis." (PMID 32308763, 2020). "In oral squamous cell carcinoma, DAZAP1 regulates the splicing of cytochrome c oxidase 16 (COX16) pre-mRNA, boosting COX16 expression to enhance mitochondrial respiration and promote tumor progression." (PMID 40401521, 2025). "We injected DAZAP1-knockdown NCI-N87 cells and control cells at different cell concentrations (1 × 104, 5 × 104, and 1 × 105 cells) into immunodeficient mice and observed the tumor formation rates." (PMID 40401521, 2025). "ND GBM pre-surgery saliva (NDT0) showed the exclusive characterization of peptide fragments of CDA, HOPX, FABP5, WIPF3, VOPP1, AHNAK, and DAZAP1 proteins, which, to the best of our knowledge, have not been previously identified in relation to GBM tumor." (PMID 41155285, 2025).
DAZAP1 also shares sentences with these, for which no sentence is quoted: hepatic carcinoma (2 papers); bipolar affective disorder (1); bladder cancer (1); neurological diseases (1); non-small cell lung carcinoma (1); ovarian carcinoma (1); pancreatic cancer (1); schizophrenia (1); teratospermia (1).